BDH1 (3-hydroxybutyrate dehydrogenase 1)
Diseases named in the same sentence as BDH1 in open-access papers (continued):
Sharing a sentence is not in itself a finding about the gene and the disease.
acute myeloid leukemia (5 papers, 2021 to 2025). Acute myeloid leukemia (AML) is a group of neoplasms arising from precursor cells committed to the myeloid cell-line differentiation. "Similarly, in acute myeloid leukemia, high BDH1 expression has been linked to the inhibition of tumor cell proliferation." (PMID 40885386, 2025). "BDH1 has shown abnormally higher expression in prostate cancer, acting as a potential metastasis‐associated gene in this cancer, while it has shown weak expression at lower levels in liver cancer, acute myeloid leukemia, and glioma tumors." (PMID 38098610, 2023). "Additionally, transcriptional inactivation of BDH1 is notably correlated with poor prognosis and shorter survival in patients with acute myeloid leukemia." (PMID 38098610, 2023). "BDH1 was reported to be down-regulated in glioblastoma and acute myeloid leukemia (AML)." (PMID 34830779, 2021). "Similarly, it was shown that other ketogenic enzymes such as ACAT1, HMGCL and/or BDH1/2 levels were significantly downregulated in ccRCC cells and patients, acute myeloid leukemia (AML) patients and AML cell lines, and nasopharyngeal carcinoma (NPC) cells." (PMID 36432618, 2022).
glioblastoma (5 papers, 2021 to 2023). The most malignant astrocytic tumor (WHO grade IV). "In addition, it was found that BDH1 is significantly down-regulated in glioblastoma and has an important role in metabolic regulation in the liver." (PMID 37434203, 2023). "In addition to ACAT1, the other two key enzymes in ketone body metabolism, BDH1 and OXT1, are also downregulated in glioblastoma." (PMID 34485115, 2021).
breast carcinoma (4 papers, 2017 to 2018). "The BDH1 protein, one of the rate-limiting enzymes that are required for ketone production, has been linked to breast cancer." (PMID 30071094, 2018). "Interestingly, we detected variable levels of mRNA expression for key enzymes of ketolysis, namely 3-hydroxybutyrate dehydrogenase 1 (BDH1), succinyl-CoA transferase (SCOT), and acetyl-CoA-acetyltransferase (ACAT), in the seven human breast cancer cell lines." (PMID 29942509, 2018). "Further investigations of common pRESs discovered that BDH1, CCDC137, and TBC1D10A transcripts contained a single non-synonymous RNA variant that was unique to breast cancer tissue compared to adjacent normal tissue; thus, further clinical validation is required." (PMID 30071094, 2018).
myocardial infarction (4 papers, 2021 to 2025). Gross necrosis of the myocardium, as a result of interruption of the blood supply to the area, as in coronary thrombosis. "A mouse model of progressive HF induced by transverse aortic constriction (TAC)/myocardial infarction exhibited upregulated BDH1 along with upregulated genes encoding ketone body transporters (MCT1 and MCT2) and increased 13C-BHB use on the basis of nuclear magnetic resonance studies." (PMID 34957264, 2021). "After being subjected to TAC and myocardial infarction (MI) surgery, the expression of BDH1 in failing hearts was significantly upregulated, indicating increased reliance on ketone bodies as a fuel." (PMID 35309549, 2021). "For example, Bdh1-knockout mice showed more severe ventricular remodeling and dysfunction after TAC/myocardial infarction, whereas in the stress overload model, the Bdh1 overexpression attenuated cardiac remodeling and DNA damage, suggesting that increased ketone utilization was adaptive." (PMID 35370704, 2022). "Cardiac-specific BDH1 knockout mice exhibit more severe ventricular remodeling and dysfunction after TAC/myocardial infarction, whereas BDH1 overexpression attenuates cardiac remodeling and DNA damage in a pressure-overloaded model." (PMID 34957264, 2021).
Hyperglycemia (3 papers, 2022 to 2024). An increased concentration of glucose in the blood. "Studies have shown that hyperglycemia reduces the expression of Bdh1 and Oxct1 in the hearts of mice." (PMID 38469146, 2024). "Hyperglycemia and hyperlipidemia in db/db mice downregulated the expression of BDH1, which subsequently downregulated the fumarate level via βOHB-AcAc-succinate-fumarate metabolic flux." (PMID 38015723, 2023). "Hepatic HADHA induction lowered fasting hyperglycemia and improved glucose and pyruvate tolerance with reduced hepatic lipid deposition in a BDH1-dependent manner." (PMID 35046401, 2022). "This suggests that BDH1 may play a protective role in DKD pathogenesis and that pathological hyperglycemia- and hyperlipidemia-induced BDH1 reduction might mediate cell injury." (PMID 38015723, 2023).
ischemia (3 papers, 2022 to 2025). A hypoperfusion of the BLOOD through an organ or tissue caused by a PATHOLOGIC CONSTRICTION or obstruction of its BLOOD VESSELS, or an absence of BLOOD CIRCULATION. "Increased expression of BDH1 increases capacity for ketolysis, improving energy reserves (i.e., p-Cr) during ischemia, as we confirm here." (PMID 40161620, 2025). "BDH1 catalyzes the initial step in the breakdown of the ketone BHB in extrahepatic tissues, and cardiac-specific knockout of BDH1 in mice leads to more severe ventricular dysfunction following ischemia." (PMID 40161620, 2025). "Both BDH1 and SCOT protein expression levels were decreased in limb tissue of mice both before and after surgery in the KD group, while the decrease was more significant in limb tissue after ischemia compared to that of mice in the ND group." (PMID 36038886, 2022).
pancreatic cancer (3 papers, 2021 to 2025). "To further investigate the role of BDH1 in pancreatic cancer, we used small interfering RNA (siRNA) technology to generate BDH1 knockdown cell lines in PaTu-8988t, MIA PaCa-2, and KPC cell lines." (PMID 40885386, 2025). "The results showed that BDH1 expression was significantly increased in pancreatic cancer tissue compared to the adjacent normal ductal tissue." (PMID 40885386, 2025).
diabetic kidney disease (2 papers, 2023 to 2024). Progressive kidney disorder caused by vascular damage to the glomerular capillaries, in patients with diabetes mellitus. "In this study, we examined the BDH1-mediated βOHB metabolic pathway in the pathogenesis of diabetic kidney disease (DKD)." (PMID 38015723, 2023).
fatty liver disease (2 papers, 2022 to 2024). A reversible condition wherein large vacuoles of triglyceride fat accumulate in liver cells via the process of steatosis. "we next detected the expression levels of Bdh1 in livers from db/m and db/db mice, a classic genetic model of obesity-associated fatty liver." (PMID 35115498, 2022). "For example, PPARα knockout mice, which exhibit impaired ketogenesis with decreased ketogenic enzymes, Hmgcs2 and Bdh1, develop hepatic steatosis." (PMID 39403635, 2024). "Investigations into key enzymes and regulators, such as HMGCS2, BDH1, PPARα, and mTORC1, highlight the intricate interplay between ketone body metabolism and fatty liver disease." (PMID 39403635, 2024).
hyperlipidemia (2 papers, 2022 to 2023). "As expected, either mRNA level or protein level of Bdh1 was obviously reduced by PA treatment in LO2 cells, indicating that the hyperlipidemia-induced Bdh1 deficiency might contribute to the pathogenesis of MAFLD." (PMID 35115498, 2022). "We suppose that reversing the disease-induced imbalance of gene expression, for instance, the hyperlipidemia-induced Bdh1 downregulation, is more reasonable than hastily inhibiting one or two members of oxidative stress pathway in the treatment of MAFLD." (PMID 35115498, 2022). "Hyperlipidemia in db/db mice leads to downregulated expression of Bdh1, which subsequently downregulates the fumarate level by metabolic flux composed of βOHB-AcAc-succinate-fumarate." (PMID 35115498, 2022). "These evidences suggest that Bdh1 may play a protective role in pathogenesis of MAFLD and hyperlipidemia-induced Bdh1 reduction in liver contribute to hepatocellular lipotoxicity." (PMID 35115498, 2022).
liver disease (2 papers, 2022 to 2025). "In conclusion, our study revealed a Bdh1-mediated molecular mechanism in pathogenesis of metabolic dysfunction related liver disease and identified Bdh1 as a novel potential therapeutic target for MAFLD." (PMID 35115498, 2022).
lymph node metastases (2 papers, 2021 to 2023). "The discriminative capacity of serum BDH1 for lymph node metastases and distant metastases evaluated with ROC analysis had 90.8% and 54.5% AUC respectively." (PMID 36919822, 2023). "The prediction rate (area under the curve [AUC]), sensitivity (true positives) and specificity (false positives) of BDH1 mRNA expression level for the prediction of lymph node metastases and distant metastases were 63.6%, 65.2%, 63.9% and 71.5%, 64.8%, 66.7% respectively." (PMID 36919822, 2023). "Transcriptome sequencing results verified that the mRNA expression values of BDH1 in patients with lymph node metastases were significantly higher than those in patients without lymph node metastases with a median (IQR) of 0.490 (−0.025–1.093) versus 0.102 (−0.540–0.663) (p = 0.002) respectively." (PMID 36919822, 2023).
malignant glioma (2 papers, 2013 to 2018). A grade III or grade IV glioma arising from the central nervous system. "It seems reasonable to hypothesize that patients with low or very low expression of key ketolytic enzymes (e.g., OXCT1, BDH1) in their malignant gliomas may respond better to the KD therapy than those patients with positive expression of these enzymes." (PMID 23829383, 2013). "They hypothesized that patients with low or very low expression of BDH1 and OXCT1 in malignant gliomas may respond better to KD therapy." (PMID 29414764, 2018).
metastatic disease (2 papers, 2020 to 2023). "Our analysis indicated that the expression of BDH1 gene was significantly downregulated in metastatic tumors when compared to the primary tumors in four out of five patients investigated." (PMID 32843722, 2020). "BDH1 could serve as a target for ketone inhibition to effectively treat advanced cancer patients with tumour recurrence and metastatic disease." (PMID 36919822, 2023).
Sepsis (2 papers, 2023 to 2025). Sepsis is defined as life-threatening organ dysfunction caused by a dysregulated host response to infection. "The myocardial concentrations of ketone body 3-hydroxybutyrate and acetoacetate were unaltered in prolonged sepsis, but gene expression of the converting enzyme 3-hydroxybutyrate dehydrogenase (Bdh1) was increased in acute and prolonged sepsis." (PMID 39821755, 2025).
steatosis (2 papers, 2022 to 2025). Increased lipid within the cytoplasm of cells. "To determine whether the diminution in hepatic fatty acid (FA) oxidation in livers of BDH1-Liver-KO mice was linked to increased steatosis or injury in mice fed a 42% kcal fat WD for 16 weeks, we performed histological and molecular analyses." (PMID 40272888, 2025). "Lastly, we induced liver injury in mice by feeding a fibrogenic choline-deficient, methionine-limited high-fat (62% kcal) diet for 16 weeks, but did not detect worsened steatosis, injury, fibrosis, or inflammation in BDH1-Liver-KO mice." (PMID 40272888, 2025).
acute promyelocytic leukemia (1 paper, 2021). An aggressive form of acute myeloid leukemia (AML), characterized by arrest of leukocyte differentiation at the promyelocyte stage, due to a specific chromosomal translocation t(15;17) in myeloid cells. "More, AML-M3, which is classified as acute promyelocytic leukemia (APL) and has a favorable prognosis, was the FAB subtype that had significantly up-regulated BDH1 expression." (PMID 34150668, 2021).
anaplastic gliomas (1 paper, 2013). "The rate limiting mitochondrial ketolytic enzymes (OXCT1 and BDH1) were either LOW or VLOW, concordantly in 14 of the 17 GBMs and in 1 of 5 anaplastic gliomas, whereas at least one of the glycolytic enzymes was POS in 13 of these 17 GBMs and all 5 anaplastic gliomas." (PMID 23829383, 2013).
autism spectrum disorder (1 paper, 2025). A spectrum of developmental disorders that includes autism, and Asperger syndrome. "These include a HAQER acting as an intronic brain enhancer in the DLGAP2 locus, a gene implicated in autism spectrum disorder and schizophrenia, and a HAQER within the 3’ UTR of BDH1 that has enhancer activity in cardiomyocytes." (PMID 41279559, 2025).
Cachexia (1 paper, 2022). Severe weight loss, wasting of muscle, loss of appetite, and general debility related to a chronic disease. "Bdh1 and HMGCS2 mRNA and protein expression levels were significantly higher in the 2-DG-treated cachexia group than in the untreated cachexia model group, indicating that ketogenesis was activated in response to the 2-DG treatment." (PMID 36230949, 2022).
colitis (1 paper, 2024). Inflammation of the colon. "We also observed a decreasing trend in proteins regulating the downstream ketogenesis pathway in colitis, including 3-hydroxy-3-methylglutaryl-CoA lyase (HMGCL), 3-hydroxybutyrate dehydrogenase 1 (BDH1), and carnitine acetyltransferase (CRAT)." (PMID 38668322, 2024).
diabetic ketoacidosis (1 paper, 2017). The metabolic condition resulted from uncontrolled diabetes mellitus, in which the shift of acid-base status of the body toward the acid side because of loss of base or retention of acids other than carbonic acid is accompanied by the accumulation of ketone bodies in body tissues and fluids. "Higher expression of BDH1 in DM may indicate accumulation of beta-hydroxybutyrate, which has been used to diagnose diabetic ketoacidosis." (PMID 28738076, 2017).
keloid (1 paper, 2025). An irregularly shaped, elevated mark on the skin caused by deposits of excessive amounts of collagen during wound healing. "By analyzing public RNA-Seq data of keloid-derived fibroblasts, we were able to identify a significant fold change in expression of OXCT1 and BDH1 in keloid-derived fibroblasts, which was consistently manifested in the whole transcriptome data for BLM-treated skin in mice." (PMID 41161389, 2025).
lung squamous cell carcinoma (1 paper, 2023). "We assessed the Cancer Genome Atlas (TCGA) dataset to characterize BDH1 expression in LUAD and lung squamous cell carcinoma (LUSC) tissues compared with adjacent normal tissues." (PMID 38098610, 2023).
Myocardial fibrosis (1 paper, 2025). "Reduction in activity of BDH1 and OXCT1 leads to exacerbation of myocardial fibrosis resulting from oxidative damage." (PMID 41161389, 2025).
pancreatic ductal adenocarcinoma (1 paper, 2025). An infiltrating adenocarcinoma that arises from the epithelial cells of the pancreas. "Moreover, we observe a significant upregulation of β-Hydroxybutyrate dehydrogenase (BDH1), a key enzyme in ketone body metabolism, in human pancreatic ductal adenocarcinoma (PDAC) tissues compared to adjacent normal pancreatic tissues." (PMID 40885386, 2025).
tumor (28 papers, 1983 to 2026). "Its dysregulation is associated with tumor microenvironment adaptation, malignant progression, and differential therapeutic responses, positioning BDH1 as both a potential prognostic biomarker and a promising therapeutic target in precision oncology." (PMID 42318484, 2026). "The intratumoral injection of BDH1 effectively promotes tumor growth in H460 xenograft mouse models." (PMID 40904702, 2025). "Compared with the vector group, the BDH1 overexpression group exhibited significantly larger tumors within the first 39 days after tumor cell injection, whereas a contrasting trend was observed in the BDH1 knockout group." (PMID 38098610, 2023). "Martinez‐Outschoorn, U. E. reported that BDH1 was critical for promoting tumour growth and metastases by ketolysis." (PMID 36919822, 2023). "The overexpression of BDH1 led to the emergence of more stem cell‐like characteristics in the tumor sphere‐forming assay, whereas fewer stem cell‐like characteristics were observed in the BDH1 knockout group." (PMID 38098610, 2023). "Our discoveries not only shed light on a hitherto overlooked tumor‐promoting role of BDH1 in LUAD but also highlight the potential of targeting BDH1 as a therapeutic approach for LUAD." (PMID 38098610, 2023). "Our findings not only reveal the previously unappreciated anti-tumor function of BDH1 in AML, but also indicate the potential of targeting BDH1 to cure AML." (PMID 34150668, 2021). "Through in vitro studies in human and mouse AML cells, we further confirmed the anti-tumor effect of BDH1 in AML." (PMID 34150668, 2021). "Next, we determined the expression of BDH1 in paired tumor samples (primary and metastatic) from patients who initially responded but develop resistance to Tam." (PMID 32843722, 2020). "We also observed that KD treatment suppressed tumor growth in nude mice with xenografts derived from HeLa cells with downregulated BDH1 and OXCT1." (PMID 29414764, 2018). "Additionally, Our results revealed that BDH1 expression is positively related to ciclosporin, a typical immunosuppressive drug with an anti-tumor effect." (PMID 40165902, 2025). "Although we demonstrate that CD8+ T cells are required for the anti-tumour effects of DR, the Cd4-Cre model used in our study deletes Bdh1 and Oxct1 in both CD4+ and CD8+ T cell lineages; therefore, we cannot exclude a contribution of ketolysis in CD4+ T cells to the observed effects." (PMID 41366157, 2025). "In addition, ectopic BDH1 expression inhibited tumor proliferation and attenuated the migration and invasion of HCC cells in vitro." (PMID 38994998, 2024). "Furthermore, in vivo administration of BDH1 effectively promoted tumour growth in H460 xenografts mice." (PMID 36919822, 2023). "Conversely, the tumor size and weight were significantly reduced in the BDH1 KO group." (PMID 38098610, 2023). "We observed that downregulation of BDH1 significantly decreased tumour growth in vivo." (PMID 36919822, 2023). "From the present research, we show the downregulation and the anti-tumor effects of BDH1 in AML." (PMID 34150668, 2021). "Taken together, our data verified that BDH1 exhibited an anti-tumor effect in MA9 AML cells." (PMID 34150668, 2021). "The anti-tumor role of BDH1 was then further confirmed in AML cells." (PMID 34150668, 2021). "Conversely, OXCT1 and ACAT1 expression levels were decreased in INSS stage 4 tumours, when compared to stage 1 in all datasets, indicating the potential reduced reliance of metastatic NB on rate‐limiting ketolytic enzymes under nutrient stress, while BDH1 levels were unchanged." (PMID 41420301, 2025). "Functionally, silencing BDH1 significantly inhibited cell proliferation and suppressed clonogenic potential in PDAC cells, highlighting a tumor-promoting role for BDH1." (PMID 40885386, 2025). "The gene expression of ketolytic enzymes BDH1, OXCT1 and ACAT1 were analysed in the context of MYCN amplification, INSS tumour stage progression and overall event free survival." (PMID 41420301, 2025).